ADAM22 (ADAM metallopeptidase domain 22)
Diseases named in the same sentence as ADAM22 in open-access papers:
ADAM22 is named in the same sentence as 47 diseases in open-access papers, as found by Europe PMC text mining. Sharing a sentence is not in itself a finding about the gene and the disease. The quoted sentences say what the papers report.
epilepsy (20 papers, 2005 to 2025). A brain disorder characterized by episodes of abnormally increased neuronal discharge resulting in transient episodes of sensory or motor neurological dysfunction, or psychic dysfunction. "Our data suggest that loss of ADAM22 function in the CNS underlies the severe rapidly progressing infantile-onset encephalopathy with epilepsy in our patient." (PMID 27066583, 2016). "Our study indicates that a significant proportion of epilepsy in patients of Roma ancestry may be caused by homozygous c.2714C > T variants in ADAM22." (PMID 37953841, 2023). "The phenotypic features in our patient also does not fully corresponds to epileptic encephalopathy as reported in previous studies with other bi-allelic ADAM22 variants, rather represent epilepsy with neurodevelopmental disorder and extend the phenotype towards milder spectrum." (PMID 37953841, 2023). "Here the authors present the crystal structure of LGI1 bound to its receptor ADAM22, which provides structural insights into epilepsy-causing LGI1 mutations and might facilitate the development of novel anti-epilepsy drugs." (PMID 29670100, 2018). "The recent identification of ADAM22 compound heterozygous mutations in a patient with severe encephalopathy and epilepsy, who inherited the mutations by healthy parents, supports the hypothesis that ADAM22 may primarily be a recessive disease gene." (PMID 27760137, 2016). "Though different in nature, each of these functions may potentially be related to epilepsy if impaired by mutations of LGI1 that prevent or disturb interactions with ADAM22 and ADAM23 receptors." (PMID 27760137, 2016). "Similarly, ADAM22 variants identified in an individual with ID and seizures produced a protein unable to bind LGI1 and a homozygous protein-truncating ADAM22 variant detected in an individual with epilepsy and ID rendered ADAM22 incapable of associating with PSD-95." (PMID 35457207, 2022). "Indeed, mutations of Adam22 has also been linked to severe epilepsy with cerebral atrophy." (PMID 28442990, 2017). "A study using a series of LGI1 and ADAM22 hypomorphic mice revealed that ~50 % of LGI1 and ~10 % of ADAM22 protein levels are sufficient to prevent lethal epilepsy." (PMID 39984135, 2025). "LGI1 is mainly expressed in hippocampus and neocortex which is a transsynapsin secretory protein, it connects presynaptic epilepsy-related ADAM23 to postsynaptic ADAM22." (PMID 36316880, 2022). "ADAM22 and ADAM23 genes were reported to be associated with progressive encephalopathy with epilepsy in human, and with genetic epilepsy in canine, respectively." (PMID 29237452, 2017). "In molecular levels, two epilepsy-related proteins in the brain, ADAM22 and ADAM23, were identified in this study, both of which are members of a disintegrin and metalloproteinase (ADAM) protein family." (PMID 28487693, 2017). "The results of this study suggest that ADAM22 is involved in human diseases such as epilepsy and peripheral neuropathy." (PMID 15876356, 2005). "In addition, we validated a downregulation of circADAM22, a circRNA derived from the epilepsy-related gene ADAM metallopeptidase domain 22 (ADAM22), only in BD." (PMID 31988434, 2020). "The absence of ligand–receptor interaction between LGI1 and ADAM22 was found to cause abnormal synaptic transmission and epilepsy in the LGI1 specifically disrupted mice." (PMID 28487693, 2017). "LGI1, ADAM22, and ADAM23 are all genetically linked to epilepsy." (PMID 27066583, 2016). "In a transgenic mouse model of epilepsy expressing a secretion-defective mutant form of human LGI1, intraperitoneal injection of 4PBA restored the binding of mutant LGI1 protein to its receptor ADAM22 and prevented the increased seizure susceptibility of the mouse model." (PMID 27519691, 2016).
epilepsy (continued). "Given that the MAGUK–ADAM22 linkage plays an essential role in hippocampal long-term potentiation, a widely accepted cellular model for learning and memory, the ADAM22–MAGUK interaction could become a therapeutic target for synaptic disorders, such as intellectual disability and epilepsy." (PMID 37953841, 2023).
breast carcinoma (6 papers, 2014 to 2023). "We have previously reported that ADAM22 protein expression in primary tumours is associated with poor disease-free survival in breast cancer patients." (PMID 33208158, 2020). "In addition, ADAM22 was shown to be associated with tolerance to chemotherapy, in breast cancer." (PMID 35003396, 2021). "The combination of NCOA1 and the transcription factor HOXC11 can activate the transcription of downstream genes, including integrin α5, ADAM22, and Myc, and can thus promote the metastasis and progression of breast cancer." (PMID 37509133, 2023). "It has been reported that extracellular matrix signaling protein ADAM22 can facilitate distant disease spread in vivo and is a crucial mechanism in the metastasis of breast cancer." (PMID 37025405, 2023). "Here potential ADAM22 on-target side effect was considered low, as insignificant ADAM22 protein expression was observed in normal healthy organs in comparison to primary and metastatic breast cancer tissue." (PMID 33208158, 2020). "Bioinformatic analysis of over-represented pathways in metastatic breast cancer identified ADAM22 as a top ranked member of the ECM-related druggable genome specific to brain metastases." (PMID 33208158, 2020). "We exploited this to develop a potential therapeutic peptide to target ADAM22-positive breast cancer cells." (PMID 33208158, 2020). "Given the elevated levels of ADAM22 in breast cancer brain metastatic tumours and the efficacy of LGI1MIM in inhibiting early metastatic events, we evaluated the potential of LGI1/ADAM22 complex as a new therapeutic strategy in breast cancer-BBB model systems." (PMID 33208158, 2020). "Here an RPPA approach was used to assess ADAM22-dependent signalling in endocrine-resistant breast cancer." (PMID 33208158, 2020). "Given the role of ADAM22 in breast cancer progression, the mechanism of action of the ADAM22 protein was investigated." (PMID 33208158, 2020). "Here we undertook ADAM22 protein target validation studies in an independent breast cancer patient cohort from a second institution (n = 843 patients)." (PMID 33208158, 2020). "Robust cell surface ADAM22 protein was found in approximately 17% of primary breast cancer tissues across all of the molecular sub-types." (PMID 33208158, 2020). "ADAM22 can enhance cell migration and inhibit differentiation in resistant model systems and is an independent predictor of poor disease-free survival in breast cancer patients." (PMID 33208158, 2020). "Here we examined the ability of ADAM22 to drive disease progression in an in vivo model of endocrine-resistant breast cancer." (PMID 33208158, 2020). "In breast cancer, ADAM22 has been identified as an estrogen receptor independent predictor of disease-free survival and has been assessed as a target for endocrine resistant breast cancer therapy." (PMID 31083655, 2019). "Tamoxifen-resistant LY2 wild-type (WT), LY2 ADAM22 overexpressing (LY2 ADAM22 KI) and ADAM22 CRISPR/Cas9 knock-out cells (LY2 ADAM22 KO) were injected into the mammary fat pad of the NOD/SCID mice to determine the effect of ADAM22 on breast cancer disease progression in vivo." (PMID 33208158, 2020). "ADAM22 expression in advanced breast cancer supports development of breast cancer brain metastasis." (PMID 33208158, 2020). "Data presented in this study suggest that targeting the ECM signalling protein ADAM22 may represent a new therapeutic strategy to treat breast cancer brain metastasis." (PMID 33208158, 2020).
encephalitis (5 papers, 2017 to 2024). An acute inflammatory process affecting the brain parenchyma. "Additionally, an in vitro study showed that anti-LGI1 from encephalitis patients blocked the binding of LGI1 to ADAM22 by neutralizing the ADAM22-binding domain of LGI1." (PMID 28725222, 2017).
Ataxia (4 papers, 2005 to 2017). Ataxia refers to impaired coordination of voluntary muscle movement. "ADAM22-deficient mice exhibited severe ataxia and premature death." (PMID 15876356, 2005). "For example, ADAM22 is necessary in PNS development and deficiency leads to hypomyelination of peripheral nerves and ataxia." (PMID 28403821, 2017). "We have reported severe ataxia, seizures, and death before weaning, accompanied with hypomyelination of the peripheral nervous system in Adam22-null mutant mice." (PMID 16504143, 2006). "On the other hand, mice lacking the Adam22 gene showed severe ataxia, exhibited marked hypomyelination of the peripheral nerves, and died before weaning." (PMID 16504143, 2006).
and epileptic encephalopathy (3 papers, 2022 to 2025). "While biallelic ADAM22 variants cause developmental and epileptic encephalopathy (DEE), the whole picture of LGI1–ADAM22/23 pathway-related diseases remains incompletely understood." (PMID 40455867, 2025).
developmental and epileptic encephalopathy (3 papers, 2022 to 2025). "Pathogenic variants of ADAM22 affecting either its biosynthesis and/or its interactions with either LGI1 and/or PSD-95 have been recently identified in individuals with developmental and epileptic encephalopathy." (PMID 37953841, 2023).
Encephalopathy (3 papers, 2016 to 2018). Encephalopathy is a term that means brain disease, damage, or malfunction. "We identified compound heterozygous loss-of-function mutations in ADAM22 in a patient with rapidly progressing severe encephalopathy with intractable seizures and profound intellectual disability." (PMID 27066583, 2016).
Intellectual disability (3 papers, 2016 to 2023). "We report 21 individuals with an autosomal recessive DEE characterized by moderate-profound intellectual disability, developmental delay and refractory seizures, in whom compound heterozygous and homozygous genetic variants in ADAM22 were identified." (PMID 35373813, 2022).
behavioural disorder (2 papers, 2023 to 2025). "Here, we describe a girl with seizures, delayed psychomotor development, and behavioural disorder, carrying a homozygous variant in ADAM22 (NM_021723.5:c.2714C > T)." (PMID 37953841, 2023). "We report the case of a girl with early-onset focal epilepsy, delayed psychomotor development and behavioural disorder carrying a novel homozygous pathogenic variant in ADAM22." (PMID 37953841, 2023).
autoimmune encephalitis (1 paper, 2015). Inflammation of the brain secondary to an immune response triggered by the body itself. "LGI1 was also considered as a possible post-synaptic receptor for Caspr2 as it is recruited within the VGKC complex where it interacts with ADAM22 and ADAM23 and LGI1 is also involved in some autoimmune encephalitis." (PMID 26217189, 2015).
cardiac hypertrophy (1 paper, 2021). "In ADAM22, as well as in ADAM12 knockout mice, cardiac hypertrophy was aggravated under pressure overload." (PMID 33400052, 2021).
developmental delay (1 paper, 2022). "This study further supports that inactivating variants in ADAM22 cause human disease and give rise to severe developmental delay and infantile-onset epilepsy." (PMID 35373813, 2022).
focal epilepsy (1 paper, 2023). A seizure caused by a localized disorder. "Here, we report a girl with early-onset focal epilepsy and mild neurologic symptoms due to an ethnically-specific homozygous missense variant in the PDZ-binding domain of ADAM22 and provide functional characterization of the pathogenicity of this variant." (PMID 37953841, 2023).
juvenile idiopathic arthritis (1 paper, 2023). Juvenile idiopathic arthritis (JIA) is the term used to describe a group of inflammatory articular disorders of unknown cause that begin before the age of 16 and last over 6 weeks. "The patient with a homozygous ADAM22 S905F variant also suffers from polyarticular form of juvenile idiopathic arthritis." (PMID 37953841, 2023).
late-onset Alzheimers disease (1 paper, 2012). This is the most common form of the disease, which happens to people age 65 and older. "Some of the other up-regulated transcripts in the VMB include members of axon guidance signaling (Rock1, Adam22), zinc finger proteins (Eif2c3 and novel KRAB box and zinc finger, C2H2 type domain containing protein) and one of the candidate genes for late onset Alzheimer's Disease (Plce1)." (PMID 22563483, 2012).
metastatic tumours (1 paper, 2020). "Moreover, ADAM22 expression correlated with known brain metastatic associated in both primary (MOCS1, n = 21, p < 0.05) and metastatic tumours (MOCS1, COL13A1, TLR4, HBEGF and PELI2, n = 21, p < 0.05)." (PMID 33208158, 2020). "Moreover, targeting ADAM22 with LGI1 induced consistent reductions in micro-metastatic disease burden in the brain." (PMID 33208158, 2020). "In line with our RNAseq studies, in matched ER-positive primary tissue and metastatic tumours (liver, brain, contralateral breast, axilla and local chest wall), where ADAM22 protein was expressed in the primary tumour, it was also expressed in the metastatic tissue." (PMID 33208158, 2020). "Furthermore, in this study, analysis of metastatic dominant ECM genes in a cohort of matched primary and metastatic tumours revealed ADAM22 as a top member of the druggable genome." (PMID 33208158, 2020).
neuroblastoma (1 paper, 2020). Neuroblastoma (NB) is the most common solid, extracranial childhood tumor. "The four UHR-NB upregulated genes (ADAM22, GAL, KLHL13 and TWIST1) were all upregulated in MYCN amplified neuroblastoma in 5 additional cohorts." (PMID 32629858, 2020).
tumor (6 papers, 2013 to 2022). "ADAM22 expression associated with clinicopathological indicators of disease progression including tumour size (p = 0.009) and grade (p = 0.02)." (PMID 33208158, 2020). "TWIST1 had a stronger association with tumor stage, as it had relatively smaller p-values than ADAM22 in both cohorts." (PMID 32629858, 2020). "ADAM22 was validated as an actionable target in in vitro, ex vivo and in patient tumour tissue (n = 843 patients)." (PMID 33208158, 2020). "Taken together, these in vitro and ex vivo studies suggest LGI1 peptide mimetic as an ADAM22-specific therapeutic with anti-tumour potential." (PMID 33208158, 2020). "Elevation of ADAM22 transcript was observed in metastatic tumours in comparison to matched primary tissue, particularly in breast to brain metastasis, as evidenced in both transcript and protein." (PMID 33208158, 2020). "The brain metastatic tissue was established and expanded in a NOD/SCID mouse and tumour-specific expression of ADAM22 was confirmed in the ex vivo tissue." (PMID 33208158, 2020). "Mice implanted with ADAM22 KO cells had significantly reduced tumour volume in comparison to mice implanted with endogenous ADAM22 or ADAM22 KI cells (p < 0.0001 and p = 0.0032, respectively)." (PMID 33208158, 2020). "Both TWIST1 and ADAM22 were upregulated for patients with higher tumor-stages in two independent cohorts, including GSE45547 and GSE120572." (PMID 32629858, 2020). "Furthermore, decreased tumour weight was observed between ADAM22 KO and WT tumours (p < 0.05)." (PMID 33208158, 2020). "It is also noteworthy that ADAM22 is highly homologous to ADAM23, and the two are thought to have similar tumour suppressor functions." (PMID 35003396, 2021).
cancer (4 papers, 2007 to 2023). A tumor composed of atypical neoplastic, often pleomorphic cells that invade other tissues. "TWIST1 and ADAM22 were also positively correlated with cancer stage, while GAL was an independent OS predictor in addition to MYCN and age." (PMID 32629858, 2020). "Unlike other family members implicated in cancer, ADAM22 lacks a functional metalloproteinase domain and may mediate its pro-tumourigenic effects through interaction with other cell surface tyrosine kinase receptors using its EGF-like domain." (PMID 33208158, 2020). "Though there has been little study to date on the non-catalytic function of ADAM proteins in cancer, a role for ADAM22 in cell adhesion and spreading in conjunction with the 14-3-3 family of signalling proteins has been described." (PMID 33208158, 2020).
neurological diseases (4 papers, 2005 to 2025). "Further detailed molecular function analysis of ADAM22 may lead to progress in uncovering the mechanisms that underlie certain human neurological diseases." (PMID 15876356, 2005).
infection (3 papers, 2014 to 2025). The state of being infected such as from the introduction of a foreign agent such as serum, vaccine, antigenic substance or organism. "Increased expression of neuromotor-related genes such as Adam22, Cacnb4 and Zic1 (activated by NF1_LV infection) and ChAt (activated by NF45_LV infection) could explain PAM symptoms such as muscle weakness and seizures." (PMID 39735262, 2024).
brain diseases (2 papers, 2021 to 2023). "Almost half of them were involved in axon-related processes (RTN4R, CNTNAP4, ADAM22, PCSK1N, NRXN1), which could indicate that the neurodegenerative mechanisms may be different between these brain diseases." (PMID 33603109, 2021).
peripheral neuropathy (1 paper, 2005). A disorder affecting the peripheral nervous system. "Further analysis of ADAM22 will provide clues to understanding the mechanisms of human diseases such as epileptic seizures and peripheral neuropathy." (PMID 15876356, 2005).
ADAM22 also shares sentences with these, for which no sentence is quoted: Progressive encephalopathy (4 papers); amnesia (2); Cerebral atrophy (2); Cognitive impairment (2); memory impairment (2); neurodevelopmental disorder (2); ovarian carcinoma (2); arthrogryposis multiplex congenita (1); autism (1); Brain atrophy (1); Cerebellar atrophy (1); channelopathies (1); cortical atrophy (1); COVID-19 (1); cystic fibrosis (1); depression (1); endometrial cancer (1); epileptic seizures (1); infantile-onset epilepsy (1); insomnia (1); leukemia (1); meningioma (1); Miscarriage (1); spastic ataxia (1).